EGFR (epidermal growth factor receptor)
Diseases named in the same sentence as EGFR in open-access papers (continued):
Sharing a sentence is not in itself a finding about the gene and the disease.
tumor (continued). "Genetic alterations that activate signaling molecules downstream of EGFR or those in parallel signaling pathways can also create conditions where EGFR signaling, initially critical to the propagation of a tumor, is no longer required." (PMID 36185288, 2022). "The combination of both monoclonal antibodies, however, resulted in the killing of both EGFR and CD38 expressing tumor cells, demonstrating that single-specificity CAR-T cells can be used to simultaneously target multiple tumor antigens and kill heterogeneous populations of cells." (PMID 36531912, 2022). "In wtCT26, there was minimal T-cell trafficking or binding to tumor cells, resulting in negligible T-cell mediated cytotoxicity or changes in cell viability, as would be expected without EGFR expression." (PMID 35177811, 2022). "To date, this is the largest real world data of the effect of primary tumor location on anti-EGFR Ab which demonstrated that tumor sidedness has no significant impact on treatment outcomes in KRASwt mCRC patients receiving second- or later-line therapy." (PMID 35242708, 2022). "Tumor cell and patient responses can become resistant to TKI therapies targeting EGFR." (PMID 34477203, 2021). "With the patient's tumor being epidermal growth factor receptor (EGFR) negative, mismatch repair (MMR) negative, 3% tumor cells PD-L1 positive with 10% tumor-associated immune cells positive, treatment with pembrolizumab was started." (PMID 33728149, 2021). "We have found that injection of 30–50 μg of 111In-labelled DOTA-ZEGFR:2377 permits saturation of EGFR expression in the liver without blocking in tumor xenografts." (PMID 33672373, 2021). "The MFs of TKI‐sensitizing EGFR mutations after nine cycles of treatment were also useful to predict the PFS, but not the tumor response." (PMID 33131198, 2021). "Interestingly, using the publicly available METABRIC and TCGA gene expression databases, tumours that had high mRNA levels of ER-β also presented the increased expression of IGF-IR, EGFR, and Ki-67, a marker of proliferating cells." (PMID 35011656, 2021). "The mRNA expression levels of various RTK genes, including VEGFR-1, VEGFR-2, PDGFR-α, PDGFR-β, anaplastic lymphoma kinase (ALK), epidermal growth factor receptor (EGFR), ErbB2, and B-RAF were compared between the tumor and adjacent normal tissues collected from the patient." (PMID 33764261, 2021). "It has been shown that tumour, node, metastasis (TNM) stage, tumor differentiation, serum laboratory indexes, or immunohistochemical (IHC) staining may be significant prognostic factors for NSCLC treated with EGFR-TKIs." (PMID 34805200, 2021). "ΔNp63α regulates key factors in tumor development, such as EGFR, MAPK, and T-cell receptor signaling pathways; chromatin remodeler pathways; and WNT, BMP, TGF-B, and NOTCH, thereby significantly contributing to oncogenic transformation and tumor onset." (PMID 34685632, 2021). "Although the histology of the original tumor has not been identified, the A-72 cells expressed EGFR, and its growth was promoted by EGF." (PMID 34944112, 2021). "EGFR overexpression was observed in most NSCLC cells; regulating EGFR signaling could help control tumorigenesis or tumor progression." (PMID 33805840, 2021). "Sym004, a new generation anti-EGFR mAb, displayed only modest anti-tumor activity in a proof of concept trial, without further clinical exploration." (PMID 34440249, 2021). "The pharmacological inhibition of PRMT5 by 5′-methylthioadenisine (MTA) or the inhibition of PRMT5 using ShRNA increased RAS-ERK1/2 activity in response to hepatocyte growth factor (HGF) and resulted in tumor suppressive effects by downregulating EGFR and RAF1 signaling in PC12 tumor cells." (PMID 33670008, 2021). "EGFR plays a role in the stimulation of vascular endothelial growth factor (VEGF), fibroblast growth factor and interleukin-8 (IL-8), which suggests that it supports tumor cell proliferation, angiogenesis, and metastasis." (PMID 34950031, 2021).
tumor (continued). "Additionally to its role in tumor bud formation and in the metastatic cascade, TGF-β1 participates in the development of treatment resistance following therapeutic EGFR inhibition via an impairment of immune responses in cooperation with prostaglandin E2." (PMID 34771518, 2021). "In PDAC, enhanced cholinergic signals could directly inhibit MAPK/EGFR, and PI3K/AKT pathways which were mediated by type 1 muscarinic receptors (CHRM1), but also could indirectly suppress tumor progression by inhibiting tumor stem cell transformation." (PMID 34572820, 2021). "Moreover, even when ER expression is still retained, molecular rewiring of the signaling pathways through the engagement of alternative RTKs such as EGFR, HER2, and FGFR can lead to the reactivation of ER-regulated transcription programs and tumor cell growth." (PMID 33809714, 2021). "We found that it was used in treatment-naïve patients as an alternative to EGFR detection in tumor tissue, when this was not feasible, and also in patients with positive or negative results of EGFR detection in tumor tissue." (PMID 34680416, 2021). "Normal and tumor cells differ in many ways, such as the presence of specific receptors such as integrin αvβx, aminopeptidase APN, peptide transporter protein PEPT1, and epidermal growth factor receptor EGFR on the surface of cancer cells." (PMID 34768793, 2021). "Gefitinib prevents the proliferation of mutant EGFR-dependent cells, enhances the presentation of tumour antigens, and promotes the apoptosis of tumour cells without affecting biological functions of immune effector cells." (PMID 34332557, 2021). "Notably, a stepwise transition may occur in NSCLC upon TKI treatment, tumor cells first reversibly enter a slow-cycling state, then regain proliferation and ultimately become drug-resistant through further epigenetic changes or via genetic modifications (such as EGFR-T790M)." (PMID 33170304, 2021). "EGFR enhances CD44-mediated tumor cell aggregation and CD44 stabilizes EGFR." (PMID 33995681, 2021). "In fact, right-sided colon cancers generally do not benefit from anti-EGFR therapy compared to left-sided tumours, due to their different embryological origin, as well as a higher number of mutations for KRAS." (PMID 34829955, 2021). "B3GNT3 was shown to be upregulated in tumor tissues as opposed to normal tissues in our sample, with a strong link to EGFR-MT LUAD." (PMID 34868228, 2021). "However, compound 1 showed the best antiproliferative activity against all tested tumor cell lines, including HCC1937 and HeLa cells, which express high levels of wild-type epidermal growth factor receptor (EGFR)." (PMID 34279406, 2021). "Based on the results of IMpower150, ACPB regimen was approved by the U.S. FDA in 2018 for the first‐line treatment of advanced nonsquamous NSCLC with no EGFR or ALK genomic tumor aberrations." (PMID 34977873, 2021). "In one patient (SM0010 [UM]), RPPA revealed significantly elevated levels of EGFR Y1173 phosphorylation, but genomics analyses of this patient’s tumor did not identify a genomic basis for EGFR activation." (PMID 33826614, 2021). "From the ginsenoside-target-pathway network, we observed that EGFR, ESR1, ESR2, HSP90AA1, and RELA are all critical genes that we should focus on, which may reveal the anti-tumor mechanism of G-Rk1 and G-Rg5." (PMID 34199025, 2021). "In H460 tumor xenograft models, the administration of SH003 or docetaxel alone diminished tumor growth, and their combination effectively killed cancer cells, with increased expression of apoptotic markers and decreased expression of p-EGFR and p-STAT3." (PMID 34445110, 2021).
tumor (continued). "CT doublet plus anti-EGFR should be recommended for 1L treatment, regardless of the primary tumor location, when cytoreduction is the goal." (PMID 34868987, 2021). "EGFR and HER2 are promising anti-tumor targets for the therapy of GBM." (PMID 33918704, 2021). "While denosumab treatment did not change cell viability, all tumor cell lines treated with 10 μM EGFR inhibitor erlotinib showed a significant decrease in cell viability to approximately 50% after six days of incubation." (PMID 34298757, 2021). "DNA use seems a good alternative, however, and this is also the second limitation of the IdyllaTM system—IdyllaTM EGFR cartridges are not certified for samples other than primary tumor biopsies included in FFPE." (PMID 34898548, 2021). "TKIs did not lead to the marked decrease in tumor cell viability in the EGFR-nonaddictive A549 and H522 cells with or without c-Src overactivation." (PMID 34367939, 2021). "Later, the same research group found that tumour secreted WISP-1/CCN4 promotes angiogenesis in oral SCC by upregulating VEGF-A via the αvβ3/FAK/c-Src pathway, which transactivates the EGFR/ERK/HIF1-α signalling pathway in oral SCC cells and increases angiogenesis-related tumour growth in vivo." (PMID 34205668, 2021). "LADs with no expression of NKX2‐1/TTF‐1 exon 1 were significantly associated with older age (p = 0.0006), no TTF‐1 immunoreactivity (p = 0.0009), and EGFR wild‐type tumours (p = 0.0009)." (PMID 34014042, 2021). "Tumor cells were positive for CD21, CD35, CD68, vimentin, and EGFR." (PMID 34516525, 2021). "RNA was isolated from formalin-fixed paraffin-embedded (FFPE) tumor biopsies collected as part of the SAKK19/09 study from epidermal growth factor receptor (EGFR) wild-type, non-squamous NSCLC patients." (PMID 32767058, 2021). "Additionally, the shRNA-mediated knockdown of LANCL2 reduced proliferation and enhanced apoptosis in the EGFR-mutant LUAD cell lines PC9 and HCC827 in vitro and suppressed PC9 xenograft tumor growth in vivo." (PMID 33568630, 2021). "Although a relationship between sensitivity to EGFR TKIs and tumor E-cadherin expression has been proposed, depletion of cadherin 1 (CDH1) by itself in EGFR-mutant therapy-naïve NSCLC cells does not lead to a loss of EGFR TKI efficacy." (PMID 34572868, 2021). "Importantly, cetuximab-resistant human tumour organoids treated with a novel inhibitor of RAC1B splicing show this same increased sensitivity to EGFR inhibition suggesting RAC1B may be a candidate therapeutic target for co-treatment with EGFR inhibitors in CRC." (PMID 33879799, 2021). "Here, we report the generation and the functional characterization of a novel EGFR-CD16 bispecific VHH that, in in vitro and ex vivo studies, enhances NK cell function to improve tumor control through simultaneous targeting of CD16 on effector NK cells and EGFR on epithelial cancers." (PMID 34771609, 2021). "Moreover, LUAD tumor LANCL2 mRNA expression and LUAD tumor EGFR mRNA expression displayed a strong positive correlation (Pearson r = 0.63)." (PMID 33568630, 2021). "We previously showed that tumor overexpression of CRIPTO, a membrane-bound and secreted protein of the EGF-CFC family that is commonly referred to as TDGF1, results in intrinsic resistance to early-generation EGFR-TKIs." (PMID 34568058, 2021). "Downregulation of linc00152 led to suppressed p-EGFR, p-AKT or p-PI3K, revealing that linc00152 may enhance tumor growth via activation of PI3K-AKT signaling pathway." (PMID 34345204, 2021). "While TMB in the tumor tissues was not assessed in the study, the findings are consistent with the fact that TMB in EGFR L858R mutated NSCLC favors better response to PD-1 ICIs." (PMID 34113560, 2021). "Our findings that STAMBP knockdown promotes EGFR degradation and suppresses LUAD tumor metastasis raise the possibility that targeting STAMBP may be a promising strategy to control LUAD progression." (PMID 34102455, 2021).
tumor (continued). "On the other hand, the inactive state of EGFR at the membrane of tumor cells could be maintained by binding Au10Peptide5-GE11 to avoid the dimerization and further inhibit the activities of tumor cells." (PMID 34322025, 2021). "Herein, we developed an epidermal growth factor receptor (EGFR) targeted ultra‐pH‐sensitive nanophotosensitizer, and systemically investigated its active targeting ability and therapeutic efficacy after the regulation of tumor vasculature and stromal barriers." (PMID 33552856, 2021). "Some surface proteins offer promising potential as tumour markers including CD91, CD317 and EGFR." (PMID 35127511, 2021). "As expected, C-7 did not trigger NK cell degranulation in the absence of EGFR expressing tumor target cells." (PMID 34771609, 2021). "The ORR was 75.7% (95% confidence interval [CI], 58.8–88.2) and was not markedly different in patients with EGFR Del19- versus L858R-positive tumours (72.7% vs 80.0%)." (PMID 33648453, 2021). "In line with previous reports, we observed low basal levels of EGFR phosphorylation (pEGFR, Tyr1068) in the TKCC-OSCC-22 tumor culture, whereas pEGFR protein levels were 55% higher in the TKCC-OSCC-16 model, suggesting activation of this signaling axis in the EGFR-amplified line." (PMID 34912708, 2021). "Although our study focused on HER2+ neoplasms, lapatinib has also been studied as a possible therapeutic alternative for triple-negative breast neoplasms, which generally show increased EGFR expression." (PMID 34204236, 2021). "While deeper genomic sequencing was outside of the scope of this study, interrogation of our KRAS wild-type tumours for other genetic drivers would be extremely valuable in evaluating the lack of response to EGFR inhibition in our patient cohort." (PMID 34956889, 2021). "To determine whether emetine suppressed the growth of PC9-ErlR tumors through the inhibition of HSF1 in vivo, we measured the protein levels of HSF1, EGFR, HSP27, and MCL1 in tumor tissues of emetine- and control-treated mice." (PMID 34203709, 2021). "For three of these phosphosites, HER3 pY1289, EGFR pY1068, and YAP pS127, at least 20% of the variance in level in the MCLP cell lines could be predicted using the linear model trained on the TCGA tumor dataset." (PMID 34010657, 2021). "Furthermore, the transcriptomics profiling revealed that tumor biomarkers changed as the cell cycle progressed and biomarkers of CA9, TK1 and EGFR were more abundantly expressed at early S stage." (PMID 34691667, 2021). "Nowadays, clinical decision-making is focused on the assessment of hormone receptors (estrogen (ER) and progesterone (PR) receptors) and of the epidermal growth factor receptor (HER-2) status, by a combination of immunohistochemical and in situ hybridization techniques on tumor cells." (PMID 34885027, 2021). "Our model demonstrated that anti-EGFR therapy is cost-effective compared to Bev in pan-RAS WT in particular left-sided tumor, but not KRAS WT population." (PMID 34012917, 2021). "Furthermore, mAbs targeting EGFR, TROP2 and α6β4 have been used for radioimmunotherapy and have shown effective localisation of primary tumours and metastatic sites in mouse models." (PMID 33917882, 2021). "We constructed a nude mouse transplanted tumor to verify whether EVs-miR-182-5p can promote tumorigenesis and metastasis in vivo through the CMTM7/EGFR/AKT axis." (PMID 34294040, 2021).
tumor (continued). "Although therapeutic mAbs against growth factor receptors EGFR and HER2 have shown promising results, their efficacy can be compromised due to the emergence of multiple resistance mechanisms attributable to the tumor's genetic and pathophysiological characteristics (detailed in section 3)." (PMID 33391547, 2021). "In summary, HAFG itself was not cytotoxic, and HAFG killed the EGFR-overexpressing tumor cells via the magnetic hyperthermia effect under AMF." (PMID 34502049, 2021). "In addition, the ERα-36/EGFR signal axis plays an important role in maintaining and actively regulating the growth of HCC tumor cells." (PMID 35096574, 2021). "In contrast, EGFR activation was not changed by dasatinib treatment, compared with that in non-treated control tumor tissues." (PMID 32989241, 2021). "These preclinical studies with improved tumor inhibition may be attributed to elucidate the interaction between VEGF and EGFR signaling pathways." (PMID 34109130, 2021). "However, in cancer-induced inflammation during tumor development, S1P2 and EGFR signaling stimulated T-helper 2 and production of IL-23 by immune cells in the tumor microenvironment." (PMID 34503163, 2021). "Early clinical successes with anti-tumor antibody therapy (anti-CD20, anti-HER2, anti-EGFR) were exclusively attributed to the interruption of their respective signaling pathways, but recent evidence suggests an essential role for innate as well as adaptive immunity in the therapeutic outcome." (PMID 33520112, 2021). "A recent study that analyzed tumor tissue of 688 patients participating in FIRE-1, CIOX, and FIRE-3 clinical trials has confirmed that AREG high level is a positive prognostic biomarker for anti-EGFR therapy in mCRC." (PMID 34326875, 2021). "In cancer cells, some signaling pathways are highly activated, such as EGFR and its downstream PI3K/Akt/mTOR pathway, which could accelerate tumor initiation and progression." (PMID 34778045, 2021). "Consistent with previous reports, none of our AA ESCC tumor samples that displayed amplified mutant EGFR showed wild type KRAS amplification." (PMID 34285259, 2021). "A major perspective for the use of circulating tumor DNA (ctDNA) in the clinical setting of non-small cell lung cancer (NSCLC) is expected as predictive factor for resistance and response to EGFR TKI therapy and, especially, as a non-invasive alternative to tissue biopsy." (PMID 34166445, 2021). "Both bispecific VHHs induced EGFR specific activation of CD16+ NK cells and tumor cell lysis regardless of KRAS tumor mutation status." (PMID 34771609, 2021). "Collectively, these data indicated that anlotinib could suppress tumor metastasis, angiogenesis, and multidrug resistance which reduced MET, EGFR, and ABCB1 expression in CRC liver metastasis and subcutaneously implanted xenograft model." (PMID 33754008, 2021). "Along these lines, in one of the very few examples of a solid tumor targeting NDCs, a cisplatin conjugated biparatopic anti-EGFR nanobody construct fused to anti-Alb was not able to demonstrate comparable tumor remission." (PMID 33859761, 2021). "The anti-EGFR TKI AG1478 has shown to increase mAb 806-reactive dimers on the surface of cells overexpressing EGFR, and the combination has of mAb806 and AG1478 resulted in enhanced anti-tumour activity in xenograft models." (PMID 34926242, 2021). "Aggressive tumors generally expressed less CysLT2R and IFN-α receptor and more EGFR, with a negative correlation between CysLT2R and EGFR expression, suggesting a potential protective role of CysLT2R against tumor progression." (PMID 35008546, 2021). "While the elevation of DR4 was detected in most tumor biopsy samples (65%; 26/40) from EGFRm NSCLC patients relapsed to treatment with first generation EGFR-TKIs, DR4 was reduced in 15% of cases (6/40) and remained unchanged in 20 of cases (8/40), among which 7 showed undetectable DR4." (PMID 33664875, 2021).